MIR216B (microRNA 216b)
Synonyms: hsa-mir-216b; MIRN216B; mir-216b
Gene: MicroRNA gene on chromosome 2 (56,000,714 to 56,000,795, reverse strand). Ensembl gene ENSG00000211520.
Gene Ontology:
Biological process: miRNA-mediated post-transcriptional gene silencing
Cellular component: RISC complex
Homologues: Orthologues: chimpanzee ptr-mir-216b (100% identical), macaque mml-mir-216b (99% identical), mouse Mir216b (93% identical), rat Mir216b (93% identical), guinea pig MIR216B (90% identical), dog MIR216B (72% identical), zebrafish dre-mir-216b (70% identical), zebrafish dre-mir-216a (41% identical). Paralogues in human: MIR216A (46% identical).
Diseases named in the same sentence as MIR216B in open-access papers:
MIR216B is named in the same sentence as 2 diseases in open-access papers, as found by Europe PMC text mining. Sharing a sentence is not in itself a finding about the gene and the disease. The quoted sentences say what the papers report.
colon cancer (1 paper, 2019). "Additionally, GALNT1 was the direct target gene of MIR216B, and SNHG7 could act as a ceRNA to sponge MIR216B, and rescue GALNT1 to facilitate colon cancer cell invasion." (PMID 31691514, 2019).
tumours (1 paper, 2024). "We identified MIR182, MIR183, MIR371, MIR373, MIR512-1, MIR512-2, MIR515-1, and MIR520e exhibiting high expression and MIR216b, MIR887, MIR9-2, and MIR9-3 exhibiting low expression in NANOG H/L tumours." (PMID 38693576, 2024).